P2RY11 (purinergic receptor P2Y11)
Description:
Receptor for ATP and ADP coupled to G proteins that activate both phosphatidylinositol-calcium and adenylyl cyclase second messenger systems. Not activated by UTP or UDP.
Synonyms: P2Y11
Tractability: Antibody: its Gene Ontology location is reachable by antibodies, with high confidence; UniProt places it where antibodies can reach, with medium confidence; UniProt predicts a signal peptide or a membrane-spanning region. PROTAC: its protein half-life has been measured; a small molecule that binds it is known.
Target class: Purine receptor; Small molecule receptor (family A GPCR); Membrane receptor; Family A G protein-coupled receptor; Nucleotide-like receptor (family A GPCR)
Gene: Protein-coding gene on chromosome 19 (10,111,693 to 10,115,372, forward strand). Ensembl gene ENSG00000244165.
Subcellular location: Cell membrane
Pathways (Reactome):
Signal Transduction: G alpha (q) signalling events; G alpha (s) signalling events; P2Y receptors
Gene Ontology:
Molecular function: G protein-coupled ATP receptor activity; neurotransmitter receptor activity; protein binding; signaling receptor activity; G protein-coupled receptor activity
Biological process: calcium-mediated signaling; cellular response to ATP; G protein-coupled receptor signaling pathway; neuronal signal transduction; activation of adenylate cyclase activity; defense response; phospholipase C-activating G protein-coupled receptor signaling pathway; G protein-coupled purinergic nucleotide receptor signaling pathway
Cellular component: plasma membrane; membrane
Genetic constraint (gnomAD): Loss-of-function variants: 5 observed, 3.87 expected, observed/expected ratio (o/e) 1.29, 90% interval 0.63 to 1.9. That is too few expected variants to judge how well the gene tolerates losing a copy. Missense variants: 670 observed, 504.06 expected, observed/expected ratio (o/e) 1.33, 90% interval 1.25 to 1.42. Synonymous variants: 307 observed, 226.66 expected, observed/expected ratio (o/e) 1.35, 90% interval 1.23 to 1.49.
Homologues: Orthologues: chimpanzee P2RY11 (98% identical), pig P2RY11 (74% identical), dog P2RY11 (70% identical), guinea pig P2RY11 (64% identical), tropical clawed frog p2ry11 (34% identical), zebrafish p2ry11 (32% identical). Paralogues in human: RXFP3 (20% identical), GPR183 (19% identical), GPR132 (17% identical), GPR174 (16% identical), GPR151 (14% identical), GPR146 (13% identical), GPR141 (11% identical).
Diseases named in the same sentence as P2RY11 in open-access papers:
P2RY11 is named in the same sentence as 32 diseases in open-access papers, as found by Europe PMC text mining. Sharing a sentence is not in itself a finding about the gene and the disease. The quoted sentences say what the papers report.
narcolepsy (7 papers, 2012 to 2024). A sleep disorder characterized by a tendency for excessive sleepiness during the day which occurs even after adequate sleep in the nighttime. "Our data expands understanding of the roles of P2RY11 in the occurrence of narcolepsy and inflammatory response." (PMID 38771396, 2024). "SNP (rs2305795) of the P2RY11 gene is found to be related to narcolepsy with cataplexy (Narcolepsy type 1, NT1), which is an immune-related disease characterized by a significant loss of HCRT (hypocretin neuropeptide precursor; also known as orexin) neurons." (PMID 38771396, 2024). "IL10RB–IFNAR1 (the IL-10 and interferon receptor gene region), ZNF365 (that encodes the transcription factor ZNF365), and P2RY11 (encodes P2Y purinoceptor 11) and the chemokine receptor CCR1–CCR3 region are all linked to narcolepsy." (PMID 36358399, 2022). "HLA-DQB1*06:02 was a major genetic factor for the onset of narcolepsy, and the T cell receptor alpha gene (TRA) and purinergic receptor P2Y, G-protein coupled, 11 gene (P2RY11) were also reported to be associated with narcolepsy." (PMID 32223758, 2020). "However, little is known about the roles of P2RY11 in the occurrence of narcolepsy and inflammatory response in vivo." (PMID 38771396, 2024). "Although the association between P2RY11 mutations or variants and NT1 has been confirmed in patients with narcolepsy, little is known about the function of P2RY11 in the development of the disease due to the absence of P2RY11 gene in rodents." (PMID 38771396, 2024). "P2RY11 is a key regulator of immune cell survival, and it may play a role in narcolepsy with cataplexy by enhancing T cell survival." (PMID 36358399, 2022). "In addition to a strong association especially with HLA DQB1*0602/DRB1*15/DR15 – DQ6 HLA type, narcolepsy has been associated with the presence of TRIB-2 antibodies, specific T-cell receptor alpha, and purinergic receptor P2RY11 genotypes." (PMID 22470463, 2012). "Narcolepsy may be the result of the immune system attacking its own hypocretin neurons, as several loci associated with narcolepsy are involved in immune system function, such as the purinergic receptor P2Y11 (P2RY11) gene." (PMID 23617951, 2013).
astrocytoma (3 papers, 2022 to 2024). "We have also performed mRNA profiling of recombinant P2Y11 in a side-by-side stimulation of astrocytoma cells with either P2RY11 overexpression (P2RY11) or P2RY11 knockdown (P2RY11-KO)." (PMID 36107259, 2022).
asthma (2 papers, 2021 to 2024). "Notably, P2RX1, P2RX4, P2RX7, P2RY1, P2RY11, and P2RY14 were revealed as the most highly expressed purinergic receptors in lung tissue, therefore suggesting that these receptors have good potential as therapeutic targets for asthma and other respiratory diseases." (PMID 35386996, 2021).
glioma (2 papers, 2019 to 2024). A benign or malignant brain and spinal cord tumor that arises from glial cells (astrocytes, oligodendrocytes, ependymal cells). "In this cell system, P2RY11 is stably expressed in the glioma cell line 1321N1, a grade II human brain astrocytoma that proved to be an efficient GPCR expression system and, above all, is naturally devoid of functional P2X and P2Y receptors." (PMID 31447857, 2019).
breast carcinoma (1 paper, 2021). "Furthermore, this study, for the first time, revealed the important functional interplay of a purinergic receptor P2Y11 and a chemokine receptor, CXCR4, in mediating the effect of ATP in inhibiting breast cancer bone metastasis." (PMID 34503103, 2021).
kidney cancer (1 paper, 2024). Primary or metastatic malignant neoplasm involving the kidney. "P2RY2, P2RY6, and P2RY11 are three Purinergic genes that we believe are closely related to KIRC but are currently less studied about kidney cancer." (PMID 38180750, 2024).
tumor (9 papers, 2013 to 2024). "In addition, excessive ATP production during tumorigenesis can disrupt the autocrine feedback mechanism mediated by P2RY11, leading to defects in T cell migration and function, affecting host immune defenses, and negatively impacting tumor patients." (PMID 38180750, 2024).
P2RY11 also shares sentences with these, for which no sentence is quoted: cancer (6 papers); acute myocardial infarction (3); Hyperglycemia (3); rheumatoid arthritis (2); atherosclerosis (1); autoimmune disease (1); berylliosis (1); bipolar disorder (1); brain astrocytoma (1); cholangiocarcinoma (1); colorectal adenocarcinoma (1); diabetes (1); dry eye (1); glioblastoma (1); hepatocellular carcinoma (1); Hypertension (1); infection (1); infectious disease (1); ischemia (1); Obesity (1); prostate carcinoma (1); rectal adenocarcinoma (1); respiratory diseases (1); schizophrenia (1); viral infection (1).